GLI2 (GLI family zinc finger 2)
Diseases named in the same sentence as GLI2 in open-access papers (continued):
Sharing a sentence is not in itself a finding about the gene and the disease.
tumor (continued). "Down-regulation of GLI transcriptional factors (GLI1 or GLI2), but not SMO signaling inhibition, reduces tumor sphere formation, a characteristics of tumor initiating cell (TIC)." (PMID 30382189, 2019). "However, our RNA-seq analysis revealed that it was not GLI1 but rather GLI2 and GLI3 that were activated in paclitaxel-resistant NSCLC cells, potentially due to alterations in the tumor microenvironment." (PMID 38228910, 2024). "SOCS1, an IFN-γ/STAT1 inhibitor, is activated by HH signaling pathway itself to create a negative feedback loop and a downstream target of GLI1 and GLI2, which upregulates its transcriptional activity and subsequently relieve the IFN-γ/STAT1 form obstructing tumor growth." (PMID 33494284, 2021). "However, in line with the lack of tumor formation in the brains of GL mice, we did not observe a significant increase in the abundance of selected Wnt and Shh targets (APC, GLI2, AXIN2, MYCN, MYC)." (PMID 34801069, 2021).
cancer (160 papers, 2009 to 2025). A tumor composed of atypical neoplastic, often pleomorphic cells that invade other tissues. "Other reports have linked ULK3 to the expression of oncogenes such as GLI2, which induces the expression of anti-apoptotic proteins, again tying in with the role of autophagy in cancer cell survival." (PMID 40831505, 2025). "Consistent with our findings, a more recent study showed that Ulk3 formed a complex with Gli2 in the nucleus in cancer-associated fibroblasts." (PMID 39792672, 2025). "As the downstream gene of the pathway, numerous reports have implicated GLI2 in the regulation of human carcinogenesis by inducing cancer cell malignant phenotypes, suggesting the potential of GLI2 as a new target for cancer treatment." (PMID 38924029, 2024). "GLI2‐expressing epithelial cells exhibit specific gene expression patterns and alterations in molecular signatures associated with cancer." (PMID 38976559, 2024). "We found that chromatin interactions, genetic alterations, and gene regulation were associated with cancer heterogeneity and subtypes in TC, and indicated the enrichment of CoMut with Gli2, HOXA10, and HIF2α around TADs in TC." (PMID 36609218, 2023). "We have identified a high correlation of NRP2 and the glioma-associated oncogene family zinc finger 2 (GLI2) transcripts in the cancer genome atlas (TCGA) cohort of BCa patients and a panel of 15 human BCa cell lines." (PMID 32038994, 2019). "SMO, in turn, activates the glioma-associated oncogene (Gli) transcription factors, Gli1 and Gli2 9, and turns on the Shh signaling pathway, which promotes cancer cell proliferation." (PMID 31417657, 2019). "Collectively, these results show that SPOP inhibits Hh pathway through destabilizing the transcriptional factor GLI2/3, which is abolished in cancers due to SPOP mutations." (PMID 30407707, 2019). "Deregulation of Hh self-renewal pathway signaling, through GLI1 and GLI2 activation, has been linked to cancer stem cell generation and therapeutic resistance in MM18–20 and other hematopoietic malignancies." (PMID 29203771, 2017). "GLI2 is known as a Kruppel-like transcription factor and is associated with cancer progression and metastasis." (PMID 27216612, 2016). "Abnormal Sonic Hedgehog signalling leads to increased transcriptional activation of its downstream effector, glioma 2 (GLI2), which is implicated in the pathogenesis of a variety of human cancers." (PMID 24481442, 2014). "Furthermore, GLI1 and GLI2 are the main transcriptional effectors, and their constitutive activation is the most important risk factor for cancer development and progression." (PMID 37504255, 2023). "To explore whether the cancer‐derived mutations affect SPOP interaction with GLI2/3, we carried out co‐IP assays and found that only wild‐type SPOP interacted with GLI2/3." (PMID 30407707, 2019). "In HCC, the abnormal regulation of GLI2 has become a key driver of malignant biological behavior of cancer cells." (PMID 40681919, 2025). "Both were reported to inhibit Gli-mediated gene activation, but GANT61 proved more potent inhibition on Gli1 and Gli2 in many cancer cell lines." (PMID 40651614, 2025). "Within this family of transcription factors, Gli1 and Gli2 constitute key transcription effectors with regard to tumorigenesis, and constitutive activation of at least one of them is essential for cancer development." (PMID 40651614, 2025). "GLI2 has been implicated in the maintenance of cancer stem cells and the promotion of EMT in various cancers." (PMID 40027190, 2025). "GLI2, a key transcription factor in the Hedgehog (Hh) signaling pathway, is regarded as a target for cancer therapy." (PMID 40133270, 2025). "RNA-seq analysis showed that after TM treatment, there was an obvious decrease in the transcription levels of GLI2, a transcriptional factor, that regulates the cancer cell proliferation and apoptosis in the SHH signaling pathway." (PMID 39881254, 2025).
cancer (continued). "Because GLI2 plays an important role in various cancers, targeted therapies targeting this pathway have become a hot topic of current research." (PMID 40681919, 2025). "In HCC, the abnormal regulation of GLI2 is closely related to malignant biological behaviors such as proliferation, invasion, migration and drug resistance of cancer cells." (PMID 40681919, 2025). "Abnormal expression of GLI2 promotes carcinogenesis by enhancing cell growth and regulating stem cell self-renewal, making it a potential therapeutic target for treating cancer or increasing the effectiveness of chemotherapy." (PMID 40133270, 2025). "Meanwhile, GLI2 also regulates the expression of matrix metalloproteinases (MMPs) and other genes, Significantly enhance the invasion and migration of cancer cells." (PMID 40681919, 2025). "Univariate Cox analysis for overall survival (OS) demonstrated that GLI1, GLI2, and GLI3 were risk factors for patients with 12, 8, and 6 types of cancer, respectively." (PMID 38498906, 2024). "This validation provides further evidence that the gene expression patterns of GLI2‐expressing cells are consistent with those observed in cancer cells, further supporting their potential role in the development of precancerous lesions." (PMID 38976559, 2024). "GSEA analysis identified mechanisms associated with GLI1, GLI2, GLI3, and GLI1/2/3 gene sets in different cancers, where they were primarily linked to EMT activation." (PMID 38498906, 2024). "Simultaneously, basal epithelial cells sense the increased ECM stiffness and undergo cancer‐like transformations, orchestrated by the transcriptomic programs of oncogenic GLI2." (PMID 38976559, 2024). "Regarding TGF-β signalling, it has been shown that this pathway can induce the expression of GLI1 and GLI2 transcription factors in several cancer cell lines, such as pancreatic ductal adenocarcinoma and breast cancer." (PMID 36765685, 2023). "High GLI2 expression has been detected in several transgenic MB mouse models, but it is not fully understood how GLI2 proceeds to drive cancer growth." (PMID 37608807, 2023). "Overexpression of GLI2 has been reported to cause resistance to targeted cancer therapy in cancer cells, and another study reported that knockdown of GLI1 and GLI2 restored sensitivity to vemurafenib-resistant cells." (PMID 36875125, 2023). "A key transcriptional target of Gli2 is PTHLH, the gene which encodes Parathyroid Hormone-related Protein (PTHrP), an osteolytic factor which is secreted by cancer upon metastasis to the bone." (PMID 37954979, 2023). "As a result, seven genes (FGF10, SERINE2, LSAMP, STXBP5, PDE5A, GLI2, FRMD6) were screened to develop the cancer associated fibroblasts (CAFs)-related risk signature (CAFRS)." (PMID 37280069, 2023). "GLI1 promotes cell proliferation by inducing cyclin D1 expression, while GLI2 is known to increase cancer cell proliferation, tumorigenicity, and metastatic potential." (PMID 35047127, 2022). "TGF-β reportedly induces the expression of the HH signaling molecule GLI2 in various human cell types and cancer cell lines." (PMID 35245440, 2022). "The results from this study suggest that LA promotes the suppressive GLI2 via acylation, thereby promoting cancer stemness." (PMID 35047127, 2022). "Conversely, the knockdown of GLI1 or TAP1 via an RNAi approach or the inhibition of GLI1/GLI2 function with GANT61 markedly improved the subpopulations’ sensitivity to all three cancer therapeutics." (PMID 34638233, 2021). "GLI family zinc finger 2 (GLI2) has been reported to be up-regulated and facilitate cancer progression in multiple malignancies." (PMID 34657624, 2021). "The same study stated that high levels of SHH, PTCH1, and GLI2 are focally expressed in the epithelium of carcinoma in situ, suggesting potential early screening possibilities for unusual HH signaling activity." (PMID 33494284, 2021).
cancer (continued). "Conversely, knockdown of ADGRG6 results in low expression of HDAC2 and GLI2, and inhibits proliferation and arrests cell cycle in cancer cells." (PMID 34809653, 2021). "GLI2 played a significant role in the pathogenesis of cancer, and some studies implicated that GLI2 mediated regulation of cytokines in TME to promote cancer cell biology." (PMID 34123589, 2021). "Taken together, these studies suggest a cooperative role of Wnt/TGF-β1 signaling that converges on GLI2 to induce PTHrP expression and consequently bony invasion in cancer." (PMID 34572373, 2021). "The abnormal expression of the transcription factors Gli1 and Gli2 in the Hh signaling pathway regulates the expression of ABCG2 in many cancers." (PMID 34659526, 2021). "TFII-I overexpression antagonized GLI2 induction by TGFβ, a known activator of GLI2 in cancer cells." (PMID 32544250, 2020). "We found higher expression of Patched1 (PTCH1), Shh, Sufu, Smo, Gli1, Gli2 and Gli3 both at mRNA and protein levels than adherent cancer cells." (PMID 32575925, 2020). "Generally, GLI1 acts mainly transcriptional activation in cancer cells, whereas GLI2 requires N-terminal processing for full activation." (PMID 32354204, 2020). "Recent reports revealed PRMT1, PRMT5, and PRMT7 regulate GLI1 and GLI2 activity in normal and cancer cells." (PMID 32859041, 2020). "They regulate GLI1 stabilization and GLI1 and GLI2 transcriptional activity in both intact cells and cancer cells." (PMID 32859041, 2020). "Gene set enrichment analysis (GSEA) using the Cancer Hallmarks database indicated that ‘Epithelial_Mesenchymal_Transition’ was the most statistically significant program activated by GLI2." (PMID 31134896, 2019). "While TGF-β is important for SMO-mediated cancer development, its role in the induction of GLI2 and GLI1 expression by inhibition of PKA activity has also been reported." (PMID 31202261, 2019). "In breast cancer cells, the kinase CIT induces Gli2 phosphorylation at S149 and its nuclear translocation, with consequent upregulation of transcription of genes involved in cancer invasiveness." (PMID 30754706, 2019). "Gli2 was localized in the cytoplasm and nucleus of cancer cells and 57% of patients showed a high level of Gli1 expression." (PMID 31417657, 2019). "The strategies to inhibit or stabilize the interaction of ARHGEF16 and its G proteins, along with GLI2 inhibition, can be used for cancer therapy." (PMID 30305138, 2018). "While knockdown of GLI1 and GLI2 sensitized cancer cells to 5-FU, the IC50 was still higher than the parental cells." (PMID 28413604, 2017). "Gli2 is overexpressed in a variety of cancers and has a direct function in cell cycle progression, apoptosis, invasion, and metastasis." (PMID 27916872, 2016). "Conversely, 14-3-3ζ stabilizes Gli2, a determinant for Smads in late-stage cancer, forming a complex with Smads to promote TGF-β-induced bone metastasis of breast cancer." (PMID 27916872, 2016). "GLI1 and GLI2 are over-expressed and thought to participate in the development and progression of various cancers, especially pancreatic ductal adenocarcinoma (PDAC)." (PMID 26318045, 2015). "In a bone metastasis model of breast cancer cell MDA-231, Gli2 in cancer cell induces secretion of PTHrP, an important osteolytic factor, and promotes bone destruction." (PMID 26343727, 2015). "The dysregulated expression of GLI1 and GLI2 plays a crucial role in the development and progression of many types of human cancers, including PDAC." (PMID 26318045, 2015). "HH signaling proteins, PTCH, SMO, and GLI2 seem to have prognostic value in cases with residual carcinoma, local recurrences, and for GLI2 distant relapses." (PMID 26588701, 2015).
cancer (continued). "Both GLI1 and GLI2 are oncogenes, induce transformation and tumorigenesis, and are constitutively activated in many types of human cancers." (PMID 24962990, 2014). "Or SPOP acts to inhibit Gli2-mediated transcriptional activation and thereby block the effect of Gli2 on the activation of target genes, thus further impact on initiation of cancer cell proliferation, migration, invasion and apoptosis." (PMID 25204354, 2014). "Since processing of the full-length GLI2 (activator form) to the repressor form is known to depend on primary cilia, we explored GLI2 processing in wt and cancer OSE cells." (PMID 23351307, 2012). "Several types of human cancers have demonstrated aberrant activation of the HH pathway by ligand-independent signaling such as, amplification of GLI1 or GLI2, mutations in PTCH or SMO, or dysregulated gene expression." (PMID 21860067, 2011). "D-finder also pinpointed highly similar D-sites in the paralogous transcription factors Gli1 and Gli2, proteins that (like Gli3) are important in regulators of stem cells and development, and which are dysregulated in several types of cancer." (PMID 20865152, 2010). "Importantly, GLI2 inhibitors effectively suppressed the growth of Smoothened (SMO) inhibitor-resistant hedgehog-driven cancer models." (PMID 40133270, 2025). "As a key transcription factor of Hedgehog, GLI2 plays an important role in many cancers." (PMID 40681919, 2025). "GLI2 can regulate the tolerance of cancer cells to anticancer agents." (PMID 40133270, 2025). "Similarly, GLI1, GLI2, and GLI3 were identified as prognostic risk factors for patients with 9, 8, and 6 types of cancer, respectively, using progression-free interval (PFI) analyses." (PMID 38498906, 2024). "Many studies have shown that GLI2 is involved in the development of cancer." (PMID 38776708, 2024). "Additionally, univariate Cox analysis of disease-specific survival (DSS) revealed that GLI1, GLI2, and GLI3 were risk factors for patients with 10, 7, and 5 types of cancer, respectively." (PMID 38498906, 2024). "Furthermore, TAB182 deletion contributes to the resistance of cells to olaparib or cisplatin, which can be rescued by silencing GLI2, a gene downstream of cancer stemness-related signaling pathways." (PMID 37953246, 2023). "GLI2 has been reported to affect stemness and drive chemoresistance in various cancers." (PMID 37953246, 2023). "Interestingly, combined inhibition of TGF-β and GLI2 reduces self-renewal and survival of cancer stem cells in colorectal cancer." (PMID 36765685, 2023). "Although several targets of Hh‐GLI2 pathway have been reported, identification of bona fide effectors downstream of GLI2 would not only deepen insights of the oncogenic mechanisms of this pathway, but also provide novel actionable target for Hh‐driven cancer." (PMID 34076957, 2021). "Indeed, we also show that interfering for MAPK15 expression strongly reduces the ability of an activated form of SMO to support cancer stem cells self-renewal, while failing to affect the same activity induced by the GLI2 oncogene." (PMID 34638386, 2021). "Our proposed Hh-GLI2 activation of stromal stem cell niche signals may also contribute to tumorignesis in different types of cancer." (PMID 31953387, 2020). "Continued studies into how TFII-I activity may be modulated in cancer cells may lead to new avenues through which GLI2 expression can be inhibited." (PMID 32544250, 2020). "Our findings provide evidence to suggest that GLI2 rearrangements are likely drivers of SSTs and may serve as potential ancillary markers for the diagnosis of these tumors, and that GLI2 should be included in panels surveying fusion genes in human cancers." (PMID 31896750, 2020).